TNF (tumor necrosis factor)
Diseases named in the same sentence as TNF in open-access papers (continued):
Sharing a sentence is not in itself a finding about the gene and the disease.
breast carcinoma (continued). "The IL-1, IL-6, IL-8, PTHrP, TNF-α, and MIP-1 secreted by metastatic breast cancer cells stimulate osteoblasts and stromal cells to secrete RANKL and subsequently affect osteoclast production in the bone microenvironment." (PMID 36497209, 2022). "NF-κB signaling pathway regulates the expression of its downstream target genes, including MMP9, TNFα, uPA and IL8, thus promoting the invasion and metastasis of breast cancer cells." (PMID 36463222, 2022). "It is suggested that BV6, in combination with TRAIL and TNFα, inhibits the autophagy process, whereas TRAIL and TNFα treatment increases autophagy in MCF7 and MDA-MB-231 breast cancer cells." (PMID 36358282, 2022). "Our previous work with breast cancer patients demonstrated that high levels of TGF-β, TNF-α, VEGF, IL-6, IL-8, and IL-10 correlated with poor prognosis, while IL-21 and CCL-2 are related to a better outcome." (PMID 36428939, 2022). "Taken together, GDC-0941 increased ILK level by upregulating TNF-α, thus affecting AKT expression and the sensitivity of breast cancer cells to GDC-0941." (PMID 35477364, 2022). "Whereas, in MDA-MB-231 breast cancer cells, an increase in apoptosis is observed from 20–30% in BV6 combined with TRAIL and TNFα compared to individual treatment with TRAIL and TNFα, i.e., 25–41%." (PMID 36358282, 2022). "We found that classical Th1 cytokines, interferon-gamma (IFN-γ) and tumor necrosis factor-alpha (TNF-α), mediated the antitumor effect of TSLP-activated CD4+ T cells against advanced breast cancer through the induction of cellular senescence." (PMID 36467403, 2022). "While determining the involvement of SIRT6 in breast cancer cell migration, SIRT6 knockdown was found to reduce TPA- or TNF-α-induced cell migration in both cell lines." (PMID 35840633, 2022). "In terms of breast cancer, TGF-β and TNF-α can not only induce EMT, but also form a stable breast cancer stem cell phenotype." (PMID 35069596, 2021). "When MSCs were added to breast cancer cells, there was less production of Th1 type cytokines IFN-γ and TNF-α, while Th2 type cytokines were significantly increased." (PMID 33860061, 2021). "Tumor necrosis factor-α (TNF α) promotes metastasis and induces EMT in breast cancer cells by inducing the expression of Twist1." (PMID 33925129, 2021). "Due to its inflammatory potency, TNF is a good prospect for localized therapy and was initially targeted to the human transferrin receptor and GD2 with cytotoxicity in vitro in breast cancer cells and murine fibroblasts." (PMID 33803078, 2021). "In our previous study, we found that CDKN1A/p21 was upregulated under TNF-α and served as a positive regulator of TNF-α-induced MMP9 gene expression in breast cancer cells." (PMID 33572115, 2021). "For instance, TNF-α induces an epithelial-mesenchymal transition (EMT) that facilitates cancer cell migration in colon cancer, prostate cancer and breast cancer by contributing to cancer initiation and progression." (PMID 33816268, 2021). "CD73 promotes metastasis of breast cancer via the expression of EGFR and IL-8, while, CD73 blockade restrains melanoma metastasis through the formation of IL-1β and TNF-α." (PMID 32902664, 2021). "Five human breast cancer cell lines, MDA-MB-231, MDA-MB-468, MCF-7, SKBR-3, and HCC-1419, were treated either with Th1 cytokines (IFN-γ and TNF-α), sunitinib, or both." (PMID 33936816, 2021). "Next, we showed that TNF-induced IP-10 production by MCF-7 breast cancer cells involves signaling via the JNK pathway as JNK inhibition by SP600125 or siRNA-mediated genetic silencing of JNK, or c-Jun attenuated the TNF-induced IP-10 production." (PMID 34572567, 2021). "In MDA-MB-231 breast cancer cell lines, overexpression of CMTM1 can promote the proliferation of breast cancer cells and resist apoptosis induced by tumor necrosis factor-α (TNF-α)." (PMID 33585698, 2021).
breast carcinoma (continued). "This contrasts with another earlier report showing that the activity of γ-secretase is required for TNF mediated TNF-R1 internalization and apoptosis induction in MCF-7 breast cancer cells." (PMID 34831323, 2021). "An isoquinoline derivative compound, berberine inhibits TNF-α induced MMP9 and cell invasion through the inhibition of AP-1 activity in MDA-MB-231human breast cancer cells." (PMID 33986746, 2021). "In breast cancer, ICAM-1 is upregulated by TNF-α and it is thought that ICAM-1 is involved in tumor cell invasion and metastasis by promoting intravasation." (PMID 34404457, 2021). "ELISA assay demonstrated that the levels of TNF-α and IL-10 in the medium of MDA-MB-231 cells co-cultured with U937 cells were higher than that in the medium of breast cancer cells alone." (PMID 33867819, 2021). "More recently, it was reported that cancer-associated fibroblast-derived CHI3L1 enhances the migration and growth of breast cancer by suppressing the T cell population and IFN-γ and TNF-α expression." (PMID 33664231, 2021). "TNF-α levels have been found to be correlated with clinical disease stage and lymph node metastasis, as well as with ER and HER2 antigen expression in breast cancer patients." (PMID 34065390, 2021). "Resistance of Cytotoxic T lymphocytes (CTLs) was also observed in the human mammary carcinoma model MCF7, which underwent EMT, following stable expression of SNAIL or after prolonged exposure to tumor necrosis factor-alpha (TNF-α)." (PMID 34576042, 2021). "The induction of apoptosis by methyl jasmonate is associated with decreased fluidity of tumor cell membranes and increased expression of tumor necrosis factor (TNFα) and its receptor 1 (TNFR1) in breast cancer cells (MDA-MB-435 and MCF7)." (PMID 34068337, 2021). "The identified target genes are involved in breast cancer, PD-L1 expression and PD-1 checkpoint pathway in cancer, MAPK signaling, apoptosis, and TNF pathways." (PMID 33440868, 2021). "In a human breast cancer cell line (MCF7), a lncRNA called Growth Arrest Specific 5 (GAS5) facilitates the transcription of TRAIL [transcription of tumor necrosis factor (TNF)-related apoptosis-inducing ligand] mRNA." (PMID 33419460, 2021). "The TNF-α pathway controls the expression of BIRC3 and helps protect breast cancer cells against apoptosis." (PMID 32333046, 2020). "Herein, we illustrate that TNF-α increases the percentage of BCSCs and TAZ expression levels in human breast cancer cell lines, and depletion of TAZ abrogates this phenotype." (PMID 32019974, 2020). "Adipokines (leptin, adiponectin, autotaxin, interleukin 6, TNFα, and HGF) secreted by adipocytes increase the mitochondrial β-oxidation in breast cancer cells." (PMID 32015297, 2020). "Our group demonstrated that stable overexpression of TNFα in BT-474 cells, a human HER2-positive breast cancer cell line, led to high activation levels of Akt and NF-κB pathways." (PMID 32391269, 2020). "More vulnerability of MCF-7/MX cell line, a mitoxantrone resistant derivative of human breast carcinoma cell line MCF-7, to the cytotoxic effects of TNF-α in comparison with its parental cell line has been reported by our group." (PMID 32742605, 2020).
breast carcinoma (continued). "In this study, a panel of four phenotypically diverse human breast cancer lines were exposed in vitro to the combination of Th1 cytokines Interferon-gamma (IFN-γ) and Tumor Necrosis Factor-alpha (TNF-α) and lipophilic statins." (PMID 32041347, 2020). "Numerous tumour-derived proteins, which are known to be involved in the establishment of the PMN were identified in the breast-cancer-derived EVs examined in this study, including VEGF, TNF-α and G-CSF." (PMID 32679759, 2020). "This study provides evidence that the addition of AIMs to CDDP would an alternative option for a combination of TNF-α inhibitor and CDDP in human breast cancer." (PMID 32784919, 2020). "In breast cancer cells, proinflammatory cytokines, such as tumor necrosis factor alpha (TNFα), upregulate CYP19 expression in breast cancer cells, suggesting the autocrine stimulation of estrogen in ER-positive breast cancer cells." (PMID 33053908, 2020). "In this study, we demonstrate that TNF-α up-regulates TAZ, a transcriptional co-activator promoting BCSC self-renewal capacity in human breast cancer cell lines." (PMID 32019974, 2020). "In the next step, we examined the dose and time dependent effect of TNF-α on MK2 activation (as indicated by phosphorylation of MK2 at T334), and the phosphorylation of SRC-3 at S857 in the breast cancer cell line MDA MB 231 and the lung cancer cell line A549." (PMID 32647362, 2020). "For instance, miR-509 was shown to be downregulated in brain metastases and promotes breast cancer cell invasion by upregulating RhoC/MMP9 and TNFα." (PMID 33002044, 2020). "Cancer-related inflammation is one of the hallmarks of cancer, and interleukin-1 (IL-1), IL-6, tumor necrosis factor alpha (TNF-α), and C-reactive protein (CRP) are widely recognized as biomarkers of systemic inflammation related to breast cancer." (PMID 33108715, 2020). "Combined breast cancer chemotherapies of CPA, MTX, and 5-fluorouracil resulted in increased levels of TNFα, IL-1β, and COX-2 in rat brain, while levels of the anti-inflammatory cytokine IL-10 decreased." (PMID 33352780, 2020). "Adipocytokines such as TNF-α, IL-1β, FGF-2, and CCL2, have been found to increase LOX expression in breast cancer." (PMID 33123472, 2020). "TNFα signaling also activates the ERK/JNK/p38 pathway leading to migration and invasion in colon cancer cells, and breast cancer cells." (PMID 32986377, 2020). "We demonstrated that TNFα has a central role in mediating proliferative effects and tumor progression in HER2-positive breast cancer in vitro and in human xenograft models." (PMID 32391269, 2020). "Adipocytokines such as TNF-α, IL-1β, FGF-2, and CCL2 have also been found to be involved in the regulation of LOX expression in breast cancer." (PMID 33123472, 2020). "Moderate exercise can reduce the expression of mRNA levels of TNF-α, IL-6, IL-18, and CRP in the livers of breast cancer mice." (PMID 32309219, 2020). "Apart from TNF-α, increased TGF-β levels in circulation of breast cancer patients can activate TAK1, which phosphorylates IKK2 as well as NIK and inhibits myogenesis by repressing the expression of MyoD." (PMID 31941005, 2020). "Using up-regulated signatures induced by ligand perturbations in LINCS L1000 module within Enrichr, the list of secreted cytokines from MDA-MB-231 was found to be statistically mimicked when breast cancer cells were treated with IL1 and TNF-α." (PMID 32883235, 2020). "In breast cancer patients, for example, PSP has been shown to upregulate cytokine genes for L-12, IL-6 and TNF-α in PBMCs." (PMID 32466253, 2020). "In the current study, we examined the inhibitory effects of DK4023 on TNFα-induced motility and invasive capability of the highly metastatic MDA-MB-231 breast cancer cells." (PMID 32708426, 2020). "Taken together, CCL2 is a promising target for inhibiting breast cancer metastasis; however, the role of brazilin in metastasis-related to CCL2 and TNFα signaling needs to be explored further." (PMID 32986377, 2020).
breast carcinoma (continued). "Cancer risk during anti-TNFα treatment in patients with inflammatory arthritis may not be not increased as reported in several literature data, even if a relative risk of 1.3 was observed for breast cancer." (PMID 32344563, 2020). "In a Phase I clinical trial, gold-NP conjugated tumor necrosis factor-α (TNF-α), namely CYT-6091, significantly inhibited tumor growth and reduced interstitial fluid pressure when combined with radiation (12/20 Gy) in breast cancer and neck cancer models." (PMID 32408880, 2020). "A strong positive correlation was found in cats with HER2-positive mammary carcinomas between the serum PD-1 levels and serum PD-L1 (r = 0.923), CTLA-4 (r = 0.975) and TNF-α (r = 0.968) levels." (PMID 32481540, 2020). "We stimulated 4T1 breast cancer cells with conditional medium of M2b macrophages and control medium, and the results showed that IDO1 was remarkably increased in TNFα enriched conditional medium." (PMID 33214550, 2020). "In this study, we analyzed the methylation status of the NFKB1 and the RELA gene in breast cancer, and found that the methylation level of the RELA gene was significantly correlated with the level of NF-κB1 transcripts under the influence of TNF-α." (PMID 31382678, 2019). "Of interest, TNFα can relay signals for direct interactions between MSC and certain breast cancer populations favoring a rare process of MSC/breast cancer cell fusion to result in the formation of breast cancer hybrid cells." (PMID 31557960, 2019). "The expression levels of different inflammatory factors including IL-1, IL-6, IL-17, TGF-β, TNF-α, NF-κB, and RONS were statistically higher in HPV- positive breast cancer patients than control samples and HPV-negative breast cancer patients." (PMID 30642295, 2019). "We observed a significantly decreased expression of Nav 1.5 after rBmK AGAP treatment which correlated with decreased expression of p-p65/NF-κB, TNF-α, and PTX3 in breast cancer cells." (PMID 30740360, 2019). "In this study, we tested three breast cancer cell lines (MDA-MB-231, ZR75-1, and MCF7) with a known difference in their sensitivity to TNF death ligands under monolayer culture." (PMID 30650534, 2019). "Recent studies have suggested that tumour necrosis factor (TNF) and its receptor 2 (TNFR2) expressed on breast cancer cells have important functional consequences." (PMID 31239840, 2019). "Tumor necrosis factor (TNF)-α induces PD-L1 expression in dendritic cells, monocytes, endothelial cells, myelodysplastic syndrome blast cells, RCC cells, prostate cells, breast cancer cells, and colon cancer cells." (PMID 31636634, 2019). "Tumor necrosis factor α (TNF-α), is another inflammatory cytokine expressed in high amounts and involved in breast cancer." (PMID 30642295, 2019). "Breast cancer lines were broadly sensitive to the combination of IFN-γ and TNF-α, as evidenced by lower metabolic activity, lower proliferation, and enhanced apoptosis, and in some cases a reversible inhibition of surface expression of HER proteins." (PMID 31666931, 2019). "The present study clearly showed that the expression of inflammatory factors including IL-1, IL-6, IL-17, TNF-α, TGF-β, NF-κB and RONS in HPV-positive breast cancer patients were higher than HPV-negative breast cancer patients and healthy controls." (PMID 30642295, 2019). "To explain these observations, we investigated actions of Th1 cytokines (TNF-α and IFN-γ) on murine and human breast cancer cell lines that varied in the surface expression of HER-family receptor tyrosine kinases." (PMID 31666931, 2019). "Fourth, In addition to MMP9, in the breast cancer cells, BMAL1 also up-regulated the expression of TNF-a, IL8, and uPA at the mRNA level, which are all target genes of NF-κB, suggesting a potential role of BMAL1 in NF-κB/MMP9 pathway." (PMID 31346317, 2019). "A study showed that in aggressive breast cancer, nuclear orphan receptor NR4A1 expression is strongly induced by the inflammatory cytokines IL-1β and TNF-α." (PMID 30213113, 2018).
breast carcinoma (continued). "We also demonstrated that GD3S gene expression is up-regulated by TNF via the NFκB pathway and that estradiol repressed GD3S expression in estrogen receptor (ER) positive breast cancer cells by preventing NFκB nuclear translocation." (PMID 29698439, 2018). "In a previous study we demonstrated that the pro-inflammatory cytokine TNF-α is a potent trigger of cell fusion between human M13SV1-Cre breast epithelial cells and human breast cancer cell lines under both normoxic and hypoxic conditions." (PMID 29636110, 2018). "Taking into account that the systemic clinical use of TNF-α is impractical due to toxicity and that IFN-γ is widely used clinically, we studied treatment of breast cancer cells with trastuzumab and pertuzumab and IFN-γ." (PMID 29796172, 2018). "Collectively, the inhibition of SOCE demonstrated decreased expression of high salt-induced release of inflammatory cytokine and chemokine, TNF-α and CXCL12, respectively, in the breast cancer cells MCF-7 and MDA-MB-231." (PMID 29861863, 2018). "As COX-2, TNF-α, VEGF-A and IL-6 are pro-metastatic and B(a)P upregulates these mediators, it is possible that B(a)P can increase breast cancer cell metastasis." (PMID 30155724, 2018). "T cell-derived cytokines, including IL-1β, TNF-α and IFN-γ, enhanced significantly TGF-β1-induced EMT in breast cancer (FMC-7) and lung cancer (A549) cell lines." (PMID 29432497, 2018). "We will analyze the expression of death receptors, such as FasL/FasR, TNF-α/TNFR1, and Bcl-2 family such as Bcl-2, Bcl-x and cytochrome c in our next experiment, to confirm the effect of AM extract on inducing breast cancer cell apoptosis via which pathway." (PMID 29523109, 2018). "It is highly efficacious in ameliorating several chronic diseases such as asthma, diabetes, cancers of breast, cervical, stomach, etc. via the inhibition of STAT3, NF-κB, PGE2, IL-6, TNF-α, etc.." (PMID 29370858, 2018). "It was previously reported that exposure of mouse mammary carcinoma cells to TGF-β and TNF induced EMT and generated cells with a CSC phenotype." (PMID 29698439, 2018). "For instance, TNFα signaling induces cdk6 gene expression in Michigan Cancer Foundation 7 (MCF7) cells, a human breast cancer cell line." (PMID 30513680, 2018). "OM-174 a TLR-2/4 agonist together with BCG demonstrated anti-cancer activity through induction of TNF-α, whilst krestin, a selective TLR-2 agonist, inhibits breast cancer in mice." (PMID 29588627, 2018). "Exogenous HA-ARD1 and HA-ARD1 S209A expression decreased cell growth after TNFα treatment; however, HA-ARD1 S209E had little effect on the growth of breast cancer cells after TNFα treatment." (PMID 30154412, 2018). "In the tumor microenvironment, cancer cells coexist with preosteoclasts and release many soluble factors such as IL8, IL11, MMP1, MMP2, TNFα, and PGE2, which determine the direct osteolytic capability of breast cancer cells." (PMID 30126457, 2018). "We demonstrate that TNF-α and IFN-γ induce senescence and apoptosis in HER2-expressing breast cancer cells in a dose-dependent manner." (PMID 29796172, 2018). "TNF-α promoted growth, migration and invasion of MCF-7 estrogen receptor (ER)- positive and MDA-MB-231 (triple negative) breast cancer cell lines, partially by inducing the expression of matrix metalloproteinases (MMPs) and dipeptidylpeptidases." (PMID 29202842, 2017). "In our study, we found that TNFα triggers IKK-mediated YAP phosphorylation and activation in breast cancer cells." (PMID 28945218, 2017). "In summary, the obtained findings suggest that there exists a TNFα evoked release of CCL2 and other LSP recruiting cytokines from human breast cancer cells, which can be attenuated by apigenin." (PMID 28441391, 2017).